GZMB (granzyme B)
Diseases named in the same sentence as GZMB in open-access papers (continued):
Sharing a sentence is not in itself a finding about the gene and the disease.
tumor (continued). "Our previous data also demonstrated that CD8 + NK1.1+ cells exerted NK- and CTL-like antitumour effects through the elimination of both tumour cells and myeloid-derived suppressor cells (MDSCs) in a granzyme B-dependent manner." (PMID 34332557, 2021). "CTLs are critical for immune-mediated tumor cell elimination through their effector molecules granzyme B and perforin." (PMID 34830805, 2021). "Specifically, tumor-infiltrating and tumor-associated NK cells from STAT3-deficient tumor-bearing mice express enhanced levels of NKG2D, CD69, FASL, granzyme B, perforin, and IFN-γ, reducing tumor growth and improving survival." (PMID 34025641, 2021). "The presence of GZMB-positive T cells in tumor was confirmed by IHC in HSC4-, NCI-H1975-, or HCC827-engrafted huNOG-FcγR−/− mice after nivolumab treatment." (PMID 34702924, 2021). "As expected, the infiltration of both CD3-positive lymphocytes and CD8-positive lymphocytes, and the expression level of the granzyme B and perforin in tumor tissue were significantly enhanced in 130 kD protein-treated mice." (PMID 33477737, 2021). "IL-10 blocking antibodies drive accumulation of tumor-infiltrating lymphocytes (TILs), release of granzyme B, and tumor cell necrosis in an in vitro human CRC culture system." (PMID 34489941, 2021). "NK cells, which are considered as the first‐line defence against tumours, releasing perforin, and granzyme B for the lysis of tumour cells." (PMID 33605033, 2021). "We found that the co-culture of tumor cells stimulated the increase of granzyme B and IFNγ in CD8+ T, but A549 exhibited resistance against CD8+ T cytotoxicity compared to HCC827." (PMID 34685495, 2021). "In tumor tissues, relationships were observed between perforin and granzyme B on the one hand and between IL-8 and CXCR1 on the other hand." (PMID 34804993, 2021). "The expression of Granzyme B (GzmB) has been shown to be a major mechanism for IL-10 mediated anti-tumor T cell responses in a mouse tumor model." (PMID 34769278, 2021). "Messai's study regarding clear cell renal cell carcinomas (CCRCC) indicated that the elevated expression of ITPR1 evoked by HIF‐2α initiated the autophagic degradation of granzyme B and abolished the NK‐induced killing effect on tumour cells." (PMID 33605033, 2021). "Perforin and granzyme B mRNA relative level in peripheral and tumor-infiltrating CD8+ T cells from GC patients was significantly reduced in comparison with those from NC (LSD-t test, all P < 0.0001)." (PMID 34620075, 2021). "TILs were measured as tumor-associated immune cells (TAICs), CD3-TILs, CD8-TILs and granzyme B-producing TILs (GZMB-TILs)." (PMID 33916194, 2021). "Due to the vacuole restriction, granzyme B cannot be transferred to the cytosol of tumor cells, hence being re-uptaken by its host and initiate a suicide-like death." (PMID 33868318, 2021). "In vivo evaluation in orthotopic A549-Luc pulmonary tumor-bearing nude murine model demonstrated tumor inhibition in the treatment groups receiving granzyme B-polymerosomes at a dose equivalent to 2.88 nmol kg−1 GrB." (PMID 34138386, 2021). "The Pt3 opT cells were significantly better than PBMC in secreting IFN-γ and granzyme B when exposed to autologous tumor organoids, consistent with their cytotoxic abilities." (PMID 34789550, 2021). "After cryo-thermal therapy, the level of Granzyme B in the spleen was increased compared to that in the tumor-bearing control group." (PMID 34681680, 2021). "The increased infiltration of CD4+ GzmB+ T cells in the central tumor area contributed to a better prognosis in the NCT group." (PMID 34631551, 2021). "Accordingly, the co-treatment of galunisertib with anti-PD-L1 treatment induced an immune response characterised with elevated T-bet and IFNγ levels in CD4+ T cells, increased GZMB production, along with increased infiltration into the tumours." (PMID 33669775, 2021).
tumor (continued). "Conversely, the percentage of CD8 + Granzyme B+ activated CTL among the total CD8+ population within the tumor compartment was lower in LM patients." (PMID 33947438, 2021). "In a variety of tumor types, IL-21 induced Granzyme B-Expressing Breg cells has been found to modulate cellular adaptive immune responses by promoting tumor avoidance mechanisms against anti-tumor immune attack." (PMID 35095898, 2021). "Tumor-infiltrating CD8+ T cells from the double cKO mice had significantly higher levels of granzyme B expression and increased numbers of IFNγ expressing cells." (PMID 34142056, 2021). "Not only did these Tc expand to a large quantity, but they also displayed high levels of granzyme B (GranzB) expression, suggestive of potent cytotoxicity, and specificity toward tumor cells assessed by reactivity to the MuLV p15E-H2Kb tetramer." (PMID 34050181, 2021). "It is found that NCT treatment did not alter the distribution of CD4+ T cells, CD8+ TRM cells (CD8+ CD103+), CD4+ TRM cells (CD4+ CD103+) and CD4+ GzmB+ T cells were significantly increased in the overall tumor area after neoadjuvant chemotherapy." (PMID 34631551, 2021). "NK cells are rapid and potent responders in the anti-tumor immune response by producing cytotoxic granules, such as perforin and GzmB or inflammatory cytokines, such as IFN-γ and TNF to kill tumor cells directly." (PMID 34742349, 2021). "In the context of IBD-associated cancer, studies in the AOM/DSS mouse model have shown that ablation of CD4+Foxp3+ Treg cells suppressed tumor growth, which was associated with increased numbers of CD8+IFN-γ+ Granzyme B-producing effector T cells." (PMID 34884543, 2021). "On the other hand, IG NAX014 administration was not able to produce any modulation on tumor-infiltrating lymphocytes as revealed by mRNA expression analysis of granzyme B and perforin in tumor masses from control and treated mice." (PMID 33800754, 2021). "CD8+ CTLs are considered the key effectors of anti-tumor immunity associated with favorable clinical outcomes since they have the capacity to directly kill tumor cells, for instance, by perforin and granzyme B release." (PMID 34073258, 2021). "Patient-derived NK cells showed a markedly decreased expression of CD16 and a trend of decreased expression of several other genes known to play a role in NK-mediated anti-tumor activity, including genes encoding for NKp46, CD69, CD62L, DAP10 and GZMB." (PMID 35116033, 2021). "This led to increased effector function at the tumor site, including enhanced cytokine production and expression of both granzyme B and Ki-67." (PMID 34050151, 2021). "On the other hand, these cells had higher per cell Granzyme B content and similar or slightly elevated cytotoxic potential against tumor cells expressing their cognate antigen." (PMID 34168650, 2021). "Next, we examined the expression of FasL and the secretion of Granzyme B in CD8+CTLs by immunofluorescence in tumor tissue." (PMID 34539408, 2021). "Type I IFNs also directly enhance CD8+ T cell responsiveness to cognate antigens and stimulate the acquisition of CTL effector function through activating the STAT3-Granzyme B (GzmB) pathway, thus ensuring tumor suppression." (PMID 34571733, 2021). "The elimination of VU-SCC-096 cells in the presence of cetuximab (80% tumor cell killing) induced a tenfold enhanced release of granzyme B compared to UM-SCC-47 cells (10% tumor cell killing)." (PMID 34681717, 2021). "CAR T cells activate GSDME cleavage in tumor cells by releasing perforin/granzyme B, thereby inducing tumor cell pyrogenesis." (PMID 34570442, 2021). "Nevertheless, IHC detected T cells expressing GZMB or Perforin in the tumor in nivolumab-treated huNOG-FcγR−/− mice, which would play a role in rejection of the tumor." (PMID 34702924, 2021).
tumor (continued). "Then we have tested the expression of CD45, CD3, CD8, ki-67, granzyme B in EL-4 tumor cells of C57BL/6 mice using flow cytometry in another in vivo study, which included 24 C57BL/6 mice bearing EL-4 tumors." (PMID 34051805, 2021). "We next looked into the gene expression profile of key effector molecules such as IFN-γ, perforin, and granzyme B, which are known to play a critical role in mechanistic execution of an effective anti-tumor response." (PMID 33117369, 2020). "The desired final outcome of the accumulation of cytotoxic CD8+ T cells, IFN-γ and granzyme B in the tumor is the destruction of cancer cells, most commonly by the induction of the apoptotic mechanism in the tumor cells." (PMID 32033490, 2020). "Meanwhile, EILSA was utilized to examine the expression of anti-tumor molecules perforin and granzyme B in lysis buffer of the spleen cells." (PMID 33330451, 2020). "We confirmed that CM from PCa cell lines induce anergy in healthy donor derived NK cells, with reduced capability to produce the anti-tumour cytokines IFNγ, TNFα and the cytotoxic factor granzyme-B." (PMID 33569050, 2020). "Instead, tumor cells sequestered granzyme B and perforin granules inside auto phagosomes for subsequent degradation." (PMID 33117715, 2020). "IHC of the tumor sections revealed an increase in CD3T cells, caspase 3 apoptotic tumor cells, and perforin and granzyme B expression in the anti-PD-1 plus CCL21-DC tumor lysate vaccine treatment group compared to diluent control and monotherapy." (PMID 32570793, 2020). "Flow cytometry analyses revealed increased frequency (4-fold) of activated CD8 T cells expressing granzyme B in the anti-PD-1 plus CCL21-DC tumor lysate vaccine treatment group in comparison to monotherapy." (PMID 32570793, 2020). "We therefore evaluated the potential contribution of Cγ receptor cytokines to the gain of GzmB in tumor-reactive CD4+ T cells." (PMID 31924474, 2020). "In both models, VISTA blockade inhibited tumor growth and improved proliferation, activation, and anti-tumor activity of T cells (increased IFNγ, granzyme B, CD107)." (PMID 32679922, 2020). "The knockdown of perforin, GSMDE blockade, as well as caspase 3 and granzyme B inhibitors were all shown to inhibit pyroptosis in tumor cells." (PMID 33643299, 2020). "Clinically, the expression levels of Granzyme B in tumor tissues are correlated with patient responses to treatment with both Nivolumab and Pembrolizumab." (PMID 33261003, 2020). "A positive correlation was also noted for PD-L1 expression in tumor biopsies and both granzyme B and perforin in CD4+ helper T cells in peripheral blood, which characteristically express very low levels of these cytolytic granule-associated proteins." (PMID 33267869, 2020). "To validate the CD4/CD8 T‐cell enhanced effector function, as suggested by the in silico analysis, we analysed the expression of IFNγ, perforin and granzyme b in the tumour‐infiltrating lymphocyte populations by flow cytometry." (PMID 32567735, 2020). "Invariant NKT cells, with properties of both NK and T cells, can also elicit an anti-tumor immune response by rapidly producing pro-inflammatory and immunomodulatory cytokines and cytotoxic perforin/granzyme B granules." (PMID 33324565, 2020). "Nevertheless, release of cytolytic granzyme B by CD8+ T cells was least potent upon coculture with autologous tumour cells (P < .0001) compared to BTZ naïve PBMCs." (PMID 32578964, 2020). "CD8+ T cells within the spleen and tumor also saw an increase in granzyme B producing cells in both mIgG1-treated and mIgG2a-treated mice." (PMID 33428585, 2020). "Qian and colleagues generated a nanoparticle-based system for the delivery of granzyme B to tumor tissues to mimics the functionality and outcome of CD8+ T and NK cell activation." (PMID 33298099, 2020). "The fraction of GzmB-expressing CD4+ T cells was increased in the tumor following αCTLA-4 treatment in accordance with the TCR transgenic data." (PMID 31924474, 2020).
tumor (continued). "In this study, we analysed the GSE108989 data set of T cells and found that NOTCH1 and FBXW7 mutations in CRC patients were associated with higher expression levels of PDCD1, CTLA4 and GZMB of tumour‐infiltrating CD8+ T cells." (PMID 32924269, 2020). "GzmB+ OT-II cells also co-expressed T-bet and were able to directly kill B16-OVA tumor in a GzmB-dependent manner." (PMID 31924474, 2020). "Since the engagement of Fc gamma receptor-expressing leukocytes—especially natural killer cells (NK)—with TZ has been shown to potently induce ADCC10, we evaluated by western blot the presence of Granzyme B in tumor lysates as readout." (PMID 32651443, 2020). "Early during tumor growth, intratumoral tumor-specific T cells co-express both Tox and Granzyme B and produce cytokines following antigen encounter." (PMID 33584701, 2020). "CD8+ is the key immune cell for tumour cell elimination, working partly through cytotoxic granule release mediated by Granzyme B (GrB)." (PMID 32410705, 2020). "CD4+ T cell transfer into lymphodepleted animals or Tregs depletion promoted GzmB expression by tumour-infiltrating CD4+, an effect prevented by IL-2 neutralization." (PMID 32680511, 2020). "Efficient tumor-lytic activity after pharmacologic Vδ2 TCR-stimulation correlates with granzyme B and IFN-γ/TNF-α production in γδ T cells, parameters which we and others found to be enhanced when IL-2, IL-12, and IL-18 are added." (PMID 31947966, 2020). "Our results showed that the expression levels of PD-L1 in tumor tissues correlated positively with expression levels of cytolytic granule components (perforin and granzyme B) in peripheral blood CD4+ T and CD56dim NK cells." (PMID 33267869, 2020). "A co-incubation of NK cells with TKD/IL-2 resulted in significant upregulation of the CD94 density on NK cells that was accompanied by an increased cytolytic activity mediated by an upregulated granzyme B production against mHsp70+ tumor cells." (PMID 32443761, 2020). "Further investigation is required to understand if the Granzyme B pathway is related to the decreased tumor growth, however the cytotoxic nature of this pathway is intriguing." (PMID 33148223, 2020). "The frequency of Trp1+GzmB-expressing cells was, however, significantly reduced in αIL-2-treated mice, both in the dLN and in the tumor." (PMID 31924474, 2020). "In MCF7 breast cancer cells, granzyme B suffered lysosome degradation, after hypoxia-induced autophagy, which inhibited NK cell-mediated tumor cell lysis." (PMID 33335860, 2020). "Tumors with a simultaneous downregulation of PRF1 and GZMB (CytAct Down) were defined as tumors with downregulated anti-tumor immunity." (PMID 32523042, 2020). "Granzyme B expression level was also significantly (p < 0.05) increased in the tumor-burdened nude mice treated with rAF-IL12." (PMID 33354412, 2020). "In fact, mice receiving CTX injection in combination with anti-PDL1 and anti-PDL2 Abs showed a 3-fold increase in CD8+/Treg ratio and upregulated IFNγ and granzyme B expression in the tumor tissue as compared to the other treatments." (PMID 32290265, 2020). "Likewise, analysis of CASP3 gene sequence revealed fourteen somatic mutations throughout a panel of tumor samples from different origins, alterations that might render this protein insensitive to GZMB-mediated cleavage and, thus, directly interfere with NK cell-mediated killing." (PMID 32466293, 2020). "The tumor tissues showed significant atrophy with islands of granzyme B positive tumor cell population surrounded by zones of fibrous connective tissue that replaced the dying tumor cells." (PMID 32552875, 2020). "Cytotoxic T cells release the serine protease granzyme B to break down type IV collagen to pass through basement membranes on the route from the blood into the tumor tissue." (PMID 32998446, 2020). "Further analysis of tumor tissues showed that the combination treatment increased CD8+ TILs, IFNγ and granzyme B in tumor tissues." (PMID 32960261, 2020).
tumor (continued). "In 4 T1 tumour models, the accumulation of PD-L1-carrying EVs in the TME caused resistance to immunotherapy by subduing granzyme B secretion." (PMID 33081785, 2020). "ENTPD1 (expressed on tumor-specific T cells), as well as the cytotoxic factors granzyme B (GZMB) and perforin 1 (PRF1), expressed by T cells and NK cells, showed progressive decrease." (PMID 33276569, 2020). "During the defense against tumors, immune cells produce pro-inflammatory cytokines such as TNF-α, IL-6, and IL-1β, and tumor-specific T cells produce perforin and granzyme B to clear tumor cells." (PMID 33299138, 2020). "Granzyme B positivity within the tumor microenvironment correlated inversely with tumor weight, with an exponential increase in tumor weight with decreasing granzyme B expression (R2 = 0.75)." (PMID 31911474, 2020). "Tumor-infiltrating T-cells also displayed a cytotoxic potential, exemplified by increased frequency of granzyme B (GZMB)-expressing cells, and proliferation, as evidenced by increased frequency of the Ki67 positive cells." (PMID 33330050, 2020). "Under hypoxic conditions, CD8 T cells can differentiate into lytic effector cells, increase the expression of interferon gamma (IFNγ), Fas ligand (FASL), granule B (GZMB), and inhibit tumor cell proliferation 24,25." (PMID 32218698, 2020). "A similar molecular mechanism was demonstrated for serpinB9, an inhibitor that can directly inhibit granzyme B; tumour cells were shown to protect themselves from cytotoxic lymphocytes by up-regulating serpinB9." (PMID 33291222, 2020). "Any tumour infiltrating lymphocytes (TILs) present in mUM were CD8+ T-cells with low expression of cytotoxic markers, such as Granzyme B, and they were typically “excluded” from the tumour core." (PMID 33008022, 2020). "Probiotic administration in mice resulted in a significant increase in interferon gamma (IFN-γ), Granzyme B and chemokine production in the tumor tissue as well as enhanced CD8+ T cell infiltration, accompanied by a suppression of tumor growth." (PMID 32033490, 2020). "In 4 T1 tumour models, the accumulation of PD-L1 on EVs in the TME caused immunotherapy resistance by subduing granzyme B secretion." (PMID 33081785, 2020). "One possibility is that anti-TIGIT blockade provides complementary anti-tumor activities to the IFN-γ pathway by reinforcing the granzyme B and perforin activations." (PMID 33117369, 2020). "Conversely, gain in KRAS, PIK3CA and SMAD4 alterations and scarce granzyme-B+ T-cells infiltration were observed when the tumor evolved towards a poly-metastatic spread." (PMID 33096795, 2020). "Qing Yi and colleagues demonstrated that Th9 cells had direct cytotoxicity to tumor cells via the secretion of Granzyme B." (PMID 32508847, 2020). "CD8+ T cells gained activation and expression of effector molecules such as IFNγ or granzyme B, which leads to repressed tumor growth or enhanced elimination of virus-infected cells." (PMID 32121590, 2020). "Granzyme B is a tumorlytic effector enzyme, which is predominantly used by cytotoxic lymphocytes and natural killer cells to lyse tumor cells." (PMID 33014820, 2020). "Infiltrated CTLs express several cytotoxic molecules such as perforin and granzyme B, which lyse tumour cells." (PMID 32439888, 2020). "Mechanistically, granzyme B (GzmB) from killer cytotoxic lymphocytes induces GSDME‐dependent pyroptosis in tumor cells, by both directly cleaving GSDME and indirectly activating caspase‐3 to cleave GSDME." (PMID 33033617, 2020). "The TRAIL-R2xCD3 BsAb mechanism of action is based on three consecutive steps, including the formation of a bridge between tumor and T cells, the activation of T cells, and the subsequent release of granzyme B and perforin that induce tumor cell killing." (PMID 33023194, 2020). "Analysis of tumor-infiltrating lymphocytes showed that DKK2 blockades led to increased levels of GZMB in tumor-infiltrating CD8+ T cells and NK cells." (PMID 32559853, 2020).